TFRC (transferrin receptor)
Diseases named in the same sentence as TFRC in open-access papers (continued):
Sharing a sentence is not in itself a finding about the gene and the disease.
leukemia (43 papers, 1997 to 2025). A malignant (clonal) hematologic disorder, involving hematopoietic stem cells and characterized by the presence of primitive or atypical myeloid or lymphoid cells in the bone marrow and the blood. "It is recognized in leukemias that the leukemic cells have enhanced iron uptake via transferrin receptor (TFRC), decreased ferroportin (efflux transporter), and increased cellular content of iron for cell proliferation." (PMID 41188278, 2025). "The leukemia cells highly and stably express the transferrin receptor CD71 on the cell membranes due to the high demand for iron and abnormal iron metabolism." (PMID 37353849, 2023). "For example, the systematic iron pool in leukemia patients had risen, and the expression level of transferrin receptor (TFR), an iron transport protein, was significantly higher in leukemia cells than in normal cells." (PMID 36499591, 2022). "An immunoconjugate containing the monoclonal antibody (5E9), against the human transferrin receptor and the protein gelonin was extremely toxic to human leukemia, lymphoma and cervical cancer cell lines." (PMID 32957689, 2020). "There is a general consensus that the occurrence of leukemia is a multistep process involving multiple genetic alterations, including transferrin receptor 1 gene, hemochromatosis (HFE) gene and some other genes involved in iron metabolism." (PMID 31519186, 2019). "In this study, we have employed transferrin which will bind specifically to the transferrin receptor which is overexpressed in leukemia cells." (PMID 30191515, 2018). "Transferrin was chosen to target RPMI8226 multiple myeloma and K562 leukemia as previous studies have shown these cells over-express the transferrin receptor." (PMID 27049725, 2016). "There has been reports showing that miR-320 is down regulated in several tumor types, and one of miR-320 ‘s downstream effects was inhibiting cell proliferation by targeting transferrin receptor 1 (CD71) in human leukemia cell line HL-60." (PMID 26487644, 2015). "In leukemia cells, enforced miR-320a expression suppresses transferrin receptor 1 expression and cell proliferation." (PMID 25924850, 2015). "We plan to initiate a clinical trial to examine the benefit of TFRC therapy against leukemia and other cancer types, including OSCC." (PMID 24890018, 2014). "Using a doxorubicin-resistant subline (K562/ADM) of human leukaemia K562 cells, the effect of immunoliposomes that targeted a cellular transferrin receptor (TFR) was examined by neutralization of doxorubicin (DOX) resistance." (PMID 9218737, 1997). "Furthermore, miRNA-320 targets the transferrin receptor CD71 in the human leukemia cell line HL-60, thereby inhibiting proliferation." (PMID 26024523, 2015). "Novel transferrin receptor-targeted liposomes delivered phosphorothioate antisense oligodeoxyribonucleotide (ODN-G3139) in TfR positive K562 leukemia cells and downregulated Bcl-2 protein in K562 cells 2-fold greater than non-targeted liposomes and 10-fold greater than free G3139." (PMID 25071577, 2014). "Our published TMT-labelled proteomics of primary leukemia samples compared to normal peripheral blood cells showed that the leukemic cells had increased iron-related proteins (FTH, FTL, TFRC, FECH, and TOM20)." (PMID 41188278, 2025). "In addition, it has been proven that in leukemia cells, intracellular HMGB1-triggered ferroptosis also engaged two other proteins, transferrin receptor (TFRC) and advanced glycosylation end-product specific receptor (AGER)." (PMID 33578654, 2021).
pancreatic cancer (42 papers, 2014 to 2026). "In pancreatic cancer, TFRC is associated with the tumor immune cycle by analyzing the relationship between TFRC and the immune cycle." (PMID 35372510, 2022). "A previous study used quantitative seroproteomics to identify antibody biomarkers in pancreatic tissue and found that TFRC is a pancreatic cancer-associated antigen." (PMID 35372510, 2022). "In this study, we used bioinformatics and biochemical experiments to verify that the expression level of TFRC was increased in pancreatic cancer tissues and was associated with a poor prognosis." (PMID 35372510, 2022). "High-TFRC is also associated with a poor prognosis and is related to tumor immunology, suggesting that TFRC may be a potential prognostic molecular predictor for pancreatic cancer patients." (PMID 35372510, 2022). "For example, when DFO and the HIF-1α inhibitor YC1 were formulated into transferrin-decorated liposome nanoparticles and targeted to transferrin receptor-expressing pancreatic cancer xenografts in mice, xenograft tumor regression was observed." (PMID 36980731, 2023). "We also analyzed the mechanism of TFRC and its role in immunotherapy using bioinformatics technology to provide suggestions for pancreatic cancer." (PMID 35372510, 2022). "To conclude, we used bioinformatics and biochemical experiments to verify that the level of TFRC is higher in pancreatic cancer than that in healthy pancreas." (PMID 35372510, 2022). "Co-expressed genes and pathway enrichment analyses were used to analyze the mechanism of the TFRC in the occurrence and development of pancreatic cancer." (PMID 35372510, 2022). "The complex relationship between DNAJB11 and TFRC in pancreatic cancer needs to be elucidated in future studies." (PMID 36209075, 2022). "Then, we investigated the difference in the expression levels of TFRC mRNA between pancreatic cancer and normal pancreas, and found that their levels were significantly higher in pancreatic cancer than that in normal pancreas." (PMID 35372510, 2022). "To analyze the clinical value of TFRC in pancreatic cancer, we examined its relationship with the clinical factors of the patients." (PMID 35372510, 2022). "The upregulated expression of TFRC was negatively correlated with the survival in patients with pancreatic cancer." (PMID 35372510, 2022). "Subsequently, we used the paired t-test to determine TFRC mRNA expression levels in pancreatic cancers and corresponding peritumoral tissues based on the data from the GEO database." (PMID 35372510, 2022). "Further studies are needed to explore the function of TFRC in pancreatic cancer as they will help to generate new ideas for the early diagnosis, targeted therapy, and prognosis judgment of patients." (PMID 35372510, 2022). "The result of western blot showed that TFRC expression was significantly lower in normal pancreatic cell (HPDE6-C7) than that in pancreatic cancer cells (PANC-1, MIAPaCa-2, PaTu8988T, SW 1990, Canpan-2, BXPC-3, HPAF-II, Capan-1)." (PMID 35372510, 2022). "Meanwhile, we verified TFRC mRNA levels in one pancreatic cell and 22 pancreatic cancer cell lines, which shows the TFRC mRNA levels were higher in most pancreatic cancer cell lines than in normal cell." (PMID 35372510, 2022). "This study can become an important step for the following basic and clinical studies of TFRC in pancreatic cancer, thus, further providing scientific arguments and evidences." (PMID 35372510, 2022). "This study deployed large sample data from databases and biochemical experiments to explore the expression level and clinical application of TFRC in pancreatic cancer." (PMID 35372510, 2022). "To verify the results of data analysis, we selected a common immune cell marker CD3 for immunohistochemical tests on tissues from three pancreatic cancer patients with high TFRC expression and observed numerous inflammatory infiltrates." (PMID 35372510, 2022).
pancreatic cancer (continued). "Both peptides have been widely used to target several cancer types overexpressing transferrin receptors (TfR1 and TfR2), including liver, prostate, breast, pancreatic cancers, and many others." (PMID 33918106, 2021). "TFRC has been studied as a reference gene in several types of tissues and different diseases showing to be stably expressed in breast, lung and pancreatic cancers." (PMID 34940125, 2021). "They demonstrated in 3D pancreatic carcinoma spheroids that both the targeting via the transferrin receptor and internalization of the nanoparticles were increased." (PMID 31875307, 2020). "TFRC, a marker of human pancreatic cancer, was also expressed at a high level, as was F2R, which encodes a G-protein-coupled receptor." (PMID 25978455, 2015). "Targeting the human transferrin receptor 1 (TfR) to deliver therapeutic oligonucleotides is a promising strategy for treating liver and pancreatic cancers, due to the overexpression of TfR on the surface of cancer cells, including HCC and metastatic PDAC cells." (PMID 40226120, 2025). "However, in pancreatic cancer, Jun overexpression was found to upregulate the mRNA transcription and protein expression of TFRC by binding to its’ promoters, thus contributing iron metabolism." (PMID 40115159, 2024). "TFRC can be used to predict immune phenotypes and immune cell infiltration in pancreatic cancer." (PMID 37760429, 2023). "Besides, SIRT3 inhibits the aggregation of iron regulatory protein 1 (IRP1), and further reduces the transferrin receptor (TfR1) expression, thus, regulating cellular iron metabolism to affect the proliferation of pancreatic cancer cells." (PMID 35832551, 2022). "Moreover, TFRC can be used as a malignant marker of pancreatic cancer and pancreatic neuroendocrine tumor." (PMID 35372510, 2022). "The surface functionalization of the micelles is realized by conjugating the carboxyl terminal XQ-2d ssDNA aptamer against CD71, a transferrin receptor highly expressed on the surface of pancreatic cancer cells, onto the amino terminal of PEO blocks via amidation reaction." (PMID 35898641, 2022). "The bioinformatics analysis showed that TFRC plays a role in the occurrence and development of pancreatic cancer mainly through signaling pathways (including cell adhesion molecule binding, condensed chromosomes, chromosome segregation, and cell cycle checkpoints)." (PMID 35372510, 2022). "Moreover, TFRC can be used for prediction of immune phenotypes and immune cell infiltration in pancreatic cancer." (PMID 35372510, 2022). "Such immunotoxins, targeting mesothelin on pancreatic cancer cells or the transferrin receptor on small cell lung cancer cells, were successfully combined with ABT-263/737 and induced death in cells that were shown to be resistant against the individual components." (PMID 28868037, 2017). "However, the mechanism of TFRC in pancreatic cancer and its relationship with clinicopathological parameters in pancreatic cancer remain unclear." (PMID 35372510, 2022). "SIRT3 overexpression is also involved in inhibiting pancreatic cancer cell growth by inhibiting iron-regulatory protein 1 (IRP1) enrichment, thereby suppressing transferrin receptor 1 (TfR1) and TfR1-mediated iron uptake and cell growth." (PMID 37175631, 2023). "Overall, TFRC can used to predict immune phenotypes, molecular subtypes in PAAD, which can lay a foundation for new immunotherapies for pancreatic cancer." (PMID 35372510, 2022). "Moreover, TFRC, as a molecular protein on the cell surface that includes cell adhesion molecule binding, may be used in the future for CAR-T therapy related to pancreatic cancer immunotherapy (by targeting TFRC to induce the patient’s own immune cells to attack the tumor)." (PMID 35372510, 2022). "Moreover, research on TFRC may generate new ideas for the immunotherapy of pancreatic cancer." (PMID 35372510, 2022).
pancreatic cancer (continued). "Overall, TFRC can be applied to predict immune phenotypes, molecular subtypes, and immune cell infiltration in PAAD, which, in turn, can create a basis for new immunotherapies for pancreatic cancer in the future." (PMID 35372510, 2022). "In addition to these two genes, Ubiquitin C (UBC) in head and neck cancer and Transferrin receptor (TFRC) and β-Glucuronidase (GUSB) in pancreatic cancer were identified to be stable as well." (PMID 28262749, 2017). "We previously reported that 89Zr-labeled TSP-A01, an antibody against transferrin receptor (TfR), is highly accumulated in a pancreatic cancer xenograft, but not in major normal organs." (PMID 25893775, 2015). "Therefore, wogonin induces lipid peroxidation by activating TF and TFRC in an iron-dependent manner but also decreases GSH levels in cells by decreases GSH levels in cells via Nrf2-GPX4 pathway, thereby inducing ferroptosis in pancreatic cancer cells." (PMID 36909174, 2023). "CX-2029, a special ADC against CD71 (transferrin receptor 1), also defined as a Probody drug conjugate (PDC), is now being tested in phase II clinical trials to treat solid tumors, head and neck cancer, non-small-cell lung cancer, pancreatic cancer and diffuse large B-cell lymphoma." (PMID 34203870, 2021).
cervical carcinoma (39 papers, 2006 to 2026). A carcinoma arising from either the exocervical squamous epithelium or the endocervical glandular epithelium. "We then used various bioinformatics methods and mathematical models to analyze those data, aiming to investigate the clinical significance of TFRC in cervical cancer and illustrate its association with tumor immunity." (PMID 40303995, 2025). "High expression of TFRC has been found in many tumors, such as lung, prostate, bladder, thyroid, and cervical cancers, and its overexpression is associated with a worse prognosis." (PMID 37940859, 2023). "TFRC is significantly upregulated in cervical cancer and is considered as a candidate gene associated with the invasion of cervical cancer." (PMID 30344797, 2018). "TFRC exhibits significant diagnostic and prognostic value in cervical cancer." (PMID 40303995, 2025). "However, the underlying mechanism of TFRC in the occurrence and malignant progression of cervical cancer is still unclear." (PMID 40303995, 2025). "Furthermore, TFRC has been closely related to human cervical cancer and is positively associated with the clinical stage and with the presence of pelvic lymph node metastases." (PMID 31516392, 2019). "Thus, TFRC has certain diagnostic and prognostic value in cervical cancer, and may become a prognostic marker of cervical cancer." (PMID 40303995, 2025). "We confirmed that TFRC expression was higher in cervical cancer tissues compared to normal cervical tissues (p < 0.0001) and HSIL (p < 0.0001) using IHC staining." (PMID 40303995, 2025). "In this study, we identified five ubiquitination-related biomarkers (MMP1, RNF2, TFRC, SPP1, and CXCL8) that are significantly associated with cervical cancer." (PMID 40809844, 2025). "This study showed that these nanoparticles were extensively internalized by HeLa cervical carcinoma cells, which exhibit high surface expression of the transferrin receptor." (PMID 40438187, 2025). "Immunohistochemistry was employed to assess TFRC protein expression in 19 cervical cancers, 16 HSILs and 15 normal cervical tissues." (PMID 40303995, 2025). "In-depth investigation into the ubiquitination-mediated regulatory mechanisms of TFRC will contribute to the development of more effective therapeutic strategies for cervical cancer." (PMID 40809844, 2025). "In summary, based on GSE63514, GSE7803, GSE9750 and TCGA data, this study found that TFRC was highly expressed in cervical cancer, which was closely related to the prognosis of tumor and OS, DSS, and PFI." (PMID 40303995, 2025). "We confirmed the higher expression of TFRC in cervical cancer tissues than in normal cervix tissues, and its expression was higher in HSIL than in normal tissues using IHC staining." (PMID 40303995, 2025). "Based on these findings, we confirmed that immunosuppression in cervical cancer is closely related to high TFRC expression." (PMID 40303995, 2025). "The relationship between TFRC and immunosuppressive genes is significantly negatively correlated in most tumor types, including cervical cancer." (PMID 40303995, 2025). "Intersection analysis revealed 18 genes that were significantly differentially expressed, including the five selected biomarkers (MMP1, RNF2, TFRC, SPP1, and CXCL8), which are significantly associated with cervical cancer progression." (PMID 40809844, 2025). "Further, we studied the protein expression of TFRC was significantly higher in the cervical cancer tissues than in normal tissues on the HPA (p < 0.0001), and representative immunohistochemical (IHC) images of normal and tumor tissues of cervix were extracted." (PMID 40303995, 2025). "We investigated the protein expression of TFRC in 19 cervical cancer samples, 16 high-grade squamous intraepithelial lesions (HSILs), and 15 normal cervical tissues using immunohistochemistry (IHC)." (PMID 40303995, 2025). "We confirmed the higher expression of TFRC in cervical cancer than in normal cervix tissues and HSIL using IHC staining." (PMID 40303995, 2025).